BOLA3 (bolA family member 3)
Description:
Acts as a mitochondrial iron-sulfur (Fe-S) cluster assembly factor that facilitates (Fe-S) cluster insertion into a subset of mitochondrial proteins. Probably acts together with NFU1.
Synonyms: MMDS2
Tractability: PROTAC: its protein half-life has been measured.
Gene: Protein-coding gene on chromosome 2 (74,135,397 to 74,147,977, reverse strand). Ensembl gene ENSG00000163170.
Subcellular location: Mitochondrion
Subcellular location (Human Protein Atlas): Mitochondria; Nuclear bodies; Cytosol
Gene Ontology:
Molecular function: protein binding
Biological process: cell redox homeostasis; intracellular iron ion homeostasis; iron-sulfur cluster assembly; protein maturation
Cellular component: iron-sulfur cluster assembly complex; mitochondrion; mitochondrial matrix
Genetic constraint (gnomAD): Loss-of-function variants: 7 observed, 7.26 expected, observed/expected ratio (o/e) 0.96, 90% interval 0.55 to 1.71. That is too few expected variants to judge how well the gene tolerates losing a copy. Missense variants: 80 observed, 82.76 expected, observed/expected ratio (o/e) 0.97, 90% interval 0.81 to 1.16. Synonymous variants: 32 observed, 26.68 expected, observed/expected ratio (o/e) 1.2, 90% interval 0.9 to 1.61.
Gene-disease validity (ClinGen):
ClinGen rates the evidence that BOLA3 causes each of these diseases.
mitochondrial disease (autosomal recessive): Definitive.
Homologues: Orthologues: chimpanzee BOLA3 (100% identical), macaque BOLA3 (99% identical), dog BOLA3 (90% identical), guinea pig BOLA3 (86% identical), mouse Bola3 (80% identical), rat Bola3 (79% identical), zebrafish bola3 (62% identical), tropical clawed frog bola3 (59% identical), Caenorhabditis elegans Y105E8A.11 (34% identical). Paralogues in human: BOLA2 (21% identical), BOLA2B (21% identical), BOLA1 (19% identical).
Diseases named in the same sentence as BOLA3 in open-access papers:
BOLA3 is named in the same sentence as 22 diseases in open-access papers, as found by Europe PMC text mining. Sharing a sentence is not in itself a finding about the gene and the disease. The quoted sentences say what the papers report.
multiple mitochondrial dysfunction syndrome (6 papers, 2015 to 2023). "However, few studies have focused on Bola3 function, other than several case reports of multiple mitochondrial dysfunction syndrome due to BOLA3 gene mutation." (PMID 33505355, 2020). "The physiological role of human BOLA3 has been better characterized in patients with Multiple Mitochondrial Dysfunction Syndrome (MMDS), a severe autosomal recessive disease caused by BOLA3 mutations." (PMID 36985206, 2023). "Defects in several proteins involved in the biosynthesis and trafficking of [4Fe-4S] clusters are associated with multiple mitochondrial dysfunctions syndromes (MMDS), with NFU1 causing MMDS1, BOLA3 causing MMDS2, IBA57 causing MMDS3, ISCA2 causing MMDS4, and ISCA1 causing MMDS5." (PMID 32151725, 2020). "Genetic defects in NFU1 (causing MMDS1, OMIM #605711), BOLA3 (causing MMDS2, OMIM #614299), and IBA57 (causing MMDS3, OMIM #615330), all factors acting in the final step of the assembly of [4Fe–4S] proteins, have been designated multiple mitochondrial dysfunction syndromes (MMDSs)." (PMID 25918518, 2015). "The methodology we have adopted was based on Pubmed searches using “multiple mitochondrial dysfunction syndrome”, “NFU1”, “BOLA3”, “IBA57”, “ISCA2”, and “ISCA1” as keywords." (PMID 34440194, 2021).
lactic acidosis (4 papers, 2014 to 2022). Metabolic acidosis characterized by the accumulation of lactate in the body. "BOLA3, which plays an essential role in iron–sulfur cluster production, was mutated in 4 unrelated patients with severe lactic acidosis and combined respiratory chain complex deficiencies (MIM 614299)." (PMID 26741492, 2016). "The His96Arg homozygous mutation of BOLA3, which was found in the Japanese population, caused severe lactic acidosis and combined respiratory chain complex deficiencies (decreased complex II activity), multiple organ failure, and hypertrophic cardiomyopathy seizures." (PMID 35883565, 2022). "Bi-allelic variants in BOLA3 cause MMDS type 2 with hyperglycinemia (MMDS2; MIM#614299), typically characterized by infantile encephalopathy, leukodystrophy, lactic acidosis, nonketotic hyperglycinemia and death in early childhood." (PMID 35883565, 2022). "Bi-allelic variants in BOLA3 cause MMDS type 2 with hyperglycinaemia (MMDS2; MIM#614299), typically characterized by infantile encephalopathy, leukodystrophy, lactic acidosis, non-ketotic hyperglycinemia and death in early childhood." (PMID 34063696, 2021).
Infantile encephalopathy (3 papers, 2016 to 2022). Encephalopathy with onset in the infantile period. "The clinical phenotypes of patients with mutations in NFU1 or BOLA3 were similar with neurological regression, infantile encephalopathy and hyperglycinemia." (PMID 27532773, 2016).
ovarian carcinoma (3 papers, 2021 to 2023). A malignant neoplasm originating from the surface ovarian epithelium. "The elevated expression of BolA1, BolA2, and BolA3 was significantly associated with the prognosis of ovarian cancer patients." (PMID 36923798, 2023). "In cancer, BolA2 and BolA3 were expressed at higher levels in ovarian cancer than in the normal adjacent tissue." (PMID 36923798, 2023). "As to BOLA3, the mRNA expression level was higher in some kinds of ovarian cancer tissues than in normal ovarian tissues." (PMID 34078439, 2021). "The mRNA and protein expression levels of BOLA2 and BOLA3 were heavily higher in ovarian cancer tissues than in normal ovarian tissues." (PMID 34078439, 2021). "In the ovarian cancer, the BOLA2 and BOLA3 were higher in cancer tissues and may act as prognostic biomarkers, and in the lung adenocarcinoma, the BOLA3 was correlated with the immune cell infiltrates." (PMID 36017386, 2022).
cardiomyopathy (1 paper, 2023). A disease of the heart muscle or myocardium proper. "Patients with BolA3 mutations were susceptible to various diseases and disorders, such as cardiomyopathy, abnormally high glycine levels in the serum, seizures, spasticity, and hypotonia." (PMID 36923798, 2023).
COVID-19 (1 paper, 2023). A disease caused by infection with severe acute respiratory syndrome coronavirus 2. "When analyzing the DEGs using the bioinformatic platform Enrichr-KG, the most relevant transcription factors potentially driving the differences in kidney gene expression between COVID-19 AKI and non-COVID-19 AKI were POLR2L, EIF3K, BOLA3, RFXANK, and ZNF576." (PMID 38003268, 2023).
endothelial dysfunction (1 paper, 2021). In vascular diseases, endothelial dysfunction is a systemic pathological state of the endothelium (the inner lining of blood vessels) and can be broadly defined as an imbalance between vasodilating and vasoconstricting substances produced by (or acting on) the endothelium. "A novel mechanism of endothelial dysfunction in PAH was based on reduced expression of BolA Family Member 3 (BOLA3) and its transcription was inhibited via histone deacetylation." (PMID 34829978, 2021).
Leigh syndrome (1 paper, 2022). A progressive neurological disease defined by specific neuropathological features associating brainstem and basal ganglia lesions. "Interestingly, pathogenic variants in another iron-sulfur cluster scaffold gene, BOLA3 (MIM: 613183), and in a gene involved in iron-sulfur cluster biosynthesis, FDXR (MIM: 103270), have previously been reported to cause Leigh syndrome." (PMID 35379322, 2022).
portal hypertension (1 paper, 2020). Increased blood pressure in the portal venous system. "Although PH can be caused by chronic liver disease and portal hypertension, PH after LT is infrequent; PH has also been reported in patients with primary mitochondrial diseases (e.g. m.3243A > G, NFU1, BOLA3), however, the mechanism underlying this remains unknown." (PMID 32703289, 2020).
pulmonary hypertension (1 paper, 2020). Increased pressure within the pulmonary circulation due to lung or heart disorder. "Recently, the first mechanism study demonstrated that Bola3 acted as a crucial lynchpin in the process of endothelial metabolic re-programming in pulmonary hypertension." (PMID 33505355, 2020). "Recently, Bola3 was reported to act a connective role between Fe-S-dependent oxidative respiration and glycine homeostasis in the process of endothelial metabolic re-programming, which is critical for pulmonary hypertension pathogenesis." (PMID 33505355, 2020).
mitochondrial disease (4 papers, 2017 to 2021). "Iron supplementation significantly elevated the expression of Cox10, the mutations of which are associated with mitochondrial disease, and Bola3 and Isca2, the mutations of which are associated with MMDS and/or oxidative phosphorylation activity." (PMID 34031430, 2021). "BOLA3-associated mitochondrial diseases follow an autosomal recessive inheritance pattern." (PMID 33574353, 2021). "BOLA3 had been identified in patients with other mitochondrial diseases, and our case was previously reported as the first evidence of this mutation in an LS patient." (PMID 28429146, 2017).
cancer (2 papers, 2022 to 2023). A tumor composed of atypical neoplastic, often pleomorphic cells that invade other tissues. "It has been suggested that BolA family members serve as assembly factors for mitochondrial iron-sulfur (Fe/S) cluster proteins that has involvement in cancer cell biology; although, the functions of BOLA1 and BOLA3 are still undefined in cancer." (PMID 36017386, 2022).
genetic diseases (1 paper, 2016). "Mutations in NFU1 and BOLA3 have been linked to genetic diseases with defects in mitochondrial Fe-S centers." (PMID 27532773, 2016). "For example, a study on patients with a rare human genetic disease suggested that proteins called BOLA3 and NFU1 might also play a role in this process." (PMID 27532773, 2016).
kidney disease (1 paper, 2025). "Renal involvement has been also described for MMDS patients harbouring mutations in BOLA3, a protein that cooperates with NFU1 in the last steps of maturation and transfer of [4Fe‐4S] clusters into target proteins, further supporting the role of [Fe‐S] cluster assembly defects on kidney disease." (PMID 40173198, 2025).
tumor (1 paper, 2024). "Additionally, analysis of iron metabolism-related gene expression revealed a downregulation of NDFIP1 and BOLA3 in tumor tissues." (PMID 39654899, 2024).
BOLA3 also shares sentences with these, for which no sentence is quoted: leukodystrophy (2 papers); Glucose intolerance (1); infection (1); lung adenocarcinoma (1); multiple mitochondrial dysfunctions syndrome 2 (1); Obesity (1); OXPHOS disease (1).